CD4 (CD4 molecule)
Diseases named in the same sentence as CD4 in open-access papers (continued):
Sharing a sentence is not in itself a finding about the gene and the disease.
bacterial infections (continued). "The requirement of cholinergic signalling through the M3R for full CD4 T cell activation and cytokine production is not restricted to Th2 responses, but also extends to synthesis of IFN-γ and protection against bacterial infection." (PMID 25629518, 2015). "In summary, these data indicate that for CD4+ T cells, OX40 signals are important for generation of effector T cells rather than TFH cells in this response to acute bacterial infection." (PMID 24771127, 2014). "Following viral or bacterial infections, the maturation and expansion of specific CD8+ T cells are not critically dependent on CD4+ T cells." (PMID 17460760, 2007). "Although these studies suggest that E-FABP is not required for lipid metabolism in CD4 and CD8 T cell homeostasis following bacterial infection, it remains unknown whether and how other lipid chaperones may contribute to regulating fatty acid metabolism." (PMID 27588422, 2016).
infectious disease (215 papers, 2004 to 2026). A disorder directly resulting from the presence and activity of a microbial, viral, or parasitic agent in humans. "CD4+ T cells play critical roles in mediating immunity against a broad array of pathogens that cause serious infectious diseases." (PMID 37116791, 2023). "Destruction of the CD4+ T cell pool increases susceptibility of the host to other infectious diseases." (PMID 30057918, 2018). "Studies have indicated that destruction of the CD4+ cell pool increases susceptibility of the host to other infectious diseases." (PMID 23849678, 2013). "In this proof-of-concept study, HR2-DoriVac, conjugated with infectious-disease-associated peptides and proteins, elicited robust neutralizing antibodies and antigen-specific CD4 and CD8 T cell activation in healthy mice, a notable contrast to some SARS-CoV-2 vaccines with limited T cell responses." (PMID 38260393, 2025). "The neonatal immune system is associated with increased vulnerability to infectious diseases which could partly be explained by an immature CD4+ T-cell compartment." (PMID 33912177, 2021). "Further immunological evaluation performed by the infectious diseases team demonstrated normal T‐cell subsets, including a preserved CD4+ count (0.93 × 109/L; RI, 0.7–1.2 × 109/L) and CD4/CD8 ratio (4.5), which was not suggestive of a primary T‐cell defect." (PMID 41584883, 2026). "CD4 T cells activated in response to infectious diseases undergo proliferation in those cells with cognate TCRs to pMHCII." (PMID 41055564, 2025). "CD4+ T cells are primarily involved in cellular immunity, controlling and clearing infections, and are an important barrier against infectious diseases." (PMID 39943158, 2025). "Th22 cells are a newly discovered class of CD4+ T cells that play important roles in inflammatory, autoimmune and infectious diseases." (PMID 39630234, 2025). "These tests were subsequently completed at the infectious disease department of a referral hospital, where a critically low CD4 count (19 cells/μL) and inverted CD4/CD8 ratio (0.04) confirmed severe immunosuppression." (PMID 40708635, 2025). "The outcome of infectious diseases and the effectiveness of vaccines are influenced by various factors, including the induction of CD4+ cells, which can affect the virologic, host physiological, or molecular level." (PMID 39331650, 2024). "A shift from a CD4+ Th1 to a CD4+ Th2 response can also be attributed to Tregs and has been confirmed in other infectious diseases." (PMID 38979428, 2024). "Indirectly, these data suggest a higher contribution of the antigen-specific CD4 T-cell response in Mpox-cured individuals, as shown in other infectious diseases." (PMID 39339995, 2024). "IL-9 is mainly generated by CD4 + cells which have been shown to be involved in infectious diseases, such as clearance of respiratory syncytial virus." (PMID 38229040, 2024). "To extend CD4+ T cell profiling to various autoimmune and infectious diseases, we performed a meta-analysis using publicly available single-cell data." (PMID 38359792, 2024). "In infectious diseases, CD4+ T cells are required for the formation and function of memory T cells, and to confer cytotoxic and migratory capacities in T cells." (PMID 37545498, 2023). "The phenotypic and functional characterization of CD4+ TRM cells was first described in infectious diseases." (PMID 37545498, 2023). "Previous studies have shown that Notch signaling is involved in the regulation of DC activation, thereby affecting DC-induced CD4+ T cell differentiation in inflammatory and infectious diseases." (PMID 38004829, 2023). "In infectious disease models, particularly chronic viral infections, IL-21 produced by CD4 T has emerged as an important modulator of CD8 T cell resident memory and exhausted cells development, homeostasis, and function." (PMID 35648273, 2022).
infectious disease (continued). "The immunosenescence-related disproportion in CD4+ and CD8+ T lymphocytes increases the risk of infectious diseases and contributes to cardiovascular, metabolic, autoimmune, and neurodegenerative diseases." (PMID 35453906, 2022). "The majority of the studies on CD4+ CTLs to date have focused on the protective roles of these cells in infectious diseases." (PMID 35468944, 2022). "Although CD8+ T cells contribute largely to the immune control of infectious diseases and tumor growth, CD4+ T cells are major immune players." (PMID 36104497, 2022). "CD25 + CD4+ T cells are regulatory T cells, Tregs, and cytokines that suppress the immune response and suppress cytokine storms in infectious diseases, so we detected the surface antibody expression of CD25 and CD69." (PMID 35632403, 2022). "In fact, these patients should be managed in collaboration with infectious disease specialists for close monitoring of plasma viral load and CD4+ T-cell count." (PMID 35203438, 2022). "In contrast, MIS-C children exhibited decreased absolute numbers of central memory, transitional memory, stem cell memory and regulatory CD4+ T cells in comparison to children with other infectious and non-infectious diseases." (PMID 36322537, 2022). "In general, whole virus inactivated adjuvanted vaccines for other infectious diseases predominantly generate low to moderate short-lived antigen specific CD4+ T helper cells but are less efficient compared to MLV in inducing CD8+ functional T cells." (PMID 36560623, 2022). "MIS-C children also exhibited significantly increased absolute numbers of naïve CD4+ T cells compared to children with other infectious and non-infectious diseases." (PMID 36322537, 2022). "Herein, a rare mutation in the IL2RG gene is described in a patient presented with allergic and infectious disorders, along with decreased number of CD4+ T cells, naïve and central memory CD4+ T cells." (PMID 34635152, 2021). "Namely, CD4+ T cells are major players involved in responses to infectious diseases, enabling B cells to differentiate into plasma cells, helping CD8+ T cells develop into cytotoxic cells, as well as are required for long-term CD8 memory generation." (PMID 33637803, 2021). "Similar to other infectious diseases, accumulating evidences have indicated that CD4+ T cells are essential to control malaria infection." (PMID 33430765, 2021). "Infectious diseases account for about two-thirds, whereas the surgical characteristics were shown in 65.1% of the CD4 < 200 cells/μl group regarding the proportion of contaminated or potentially contaminated incisions." (PMID 34616598, 2021). "Before leukapheresis a clinical check-up with screening for infectious disease markers, immunophenotyping by flow cytometry for CD4+ and CD19+ cells and differential blood count has to be performed for all patients." (PMID 32429189, 2020). "Missing data was of concern, particularly to those variables that influence LTFU like viral load and CD4 cell count in addition to non-communicable diseases comorbidities." (PMID 33028546, 2020). "Of the communicable disease group, the CD4 count POC test was the most desirable, requested by 37% of the clinics." (PMID 29843711, 2018). "Given that CD4+ T cells showed enhanced activation phenotype under NLRC3-deficient conditions, we investigated the role of NLRC3 in the infectious disease." (PMID 30133544, 2018). "Further studies to investigate the humoral immune response in HIV infected individuals in relation to CD4 counts against various infectious diseases are warranted in developing countries." (PMID 29515749, 2017). "The identification and study of antigen-specific CD4 T cells, both in peripheral blood and in tissues, is key for a broad range of immunological research, including vaccine responses and infectious diseases." (PMID 29065175, 2017).
infectious disease (continued). "There is a need to investigate humoral immune responses in HIV infected individuals in relation to CD4 counts against various infectious diseases in developing countries where most of these infections are endemic." (PMID 29515749, 2017). "A definitive study of the function of Foxp3, in either CD4 or γδ T-cells, to demonstrate their specific actions within veterinary infectious disease remains to be completed." (PMID 28871261, 2017). "CD4 cells are a type of white blood cells that plays a significant role in protecting humans from infectious diseases." (PMID 27843481, 2016). "The discovery that phenotypically unique subsets of CXCR5+ memory CD4 T cells have recall potential specific for Tfh function invites important questions for future study that will inform vaccination strategies for infectious diseases." (PMID 25699040, 2015). "Besides, IFN-ɣ, CD4+ T-cells also demonstrated to be the main source of IL-17A, a key cytokine in the development of a Th17 immune response, which has been implicated in autoimmune and autoinflammatory diseases, but also has proven to be significant in overcoming several infectious diseases." (PMID 26352261, 2015). "The identification and characterization of CD4 Tcm and Tem subpopulations in cattle should prove useful for development of vaccines and the understanding of the immunopathogenesis for many infectious diseases of cattle." (PMID 25879774, 2015). "Effective B cell responses to infectious diseases or immunization require the assistance of CD4+ helper T cells." (PMID 25699040, 2015). "Additional POC CD4+ T-cell tests in development include a multiplex infectious disease test (MBio Diagnostics) and a semiquantitative, electricity-free CD4+ T-cell blood test (Zyomyx)." (PMID 24579041, 2014). "In contrast, and despite their first description more than three decades ago, the precise contribution of cytotoxic CD4+T cells to the resolution of infectious diseases has remained a matter of debate." (PMID 23565245, 2013). "Simultaneous production of multiple cytokines and expression of certain phenotypic markers by either CD4 or CD8 T cells is proposed to represent a correlate of vaccine mediated protection against various infectious diseases." (PMID 24146841, 2013). "Interestingly, T helper 17 (Th17) cells, another newly identified subset of CD4+ cells with retinoid orphan nuclear receptor γ t (RORγt) as the specific transcriptional factor, are closely-linked with Treg cells and have also been implicated in autoimmune and infectious diseases." (PMID 22745730, 2012). "Both Teff and Tem CD4 T cells can protect in various infectious disease models, and for CD8 T cells, in some cases, they are more potent than resting memory cells." (PMID 21124875, 2010). "These cells constitute about 2–3% of human CD4+ T cells, and they have increasingly been found to play conflicting roles in both autoimmune and infectious disease." (PMID 19557183, 2009). "Indeed, the CD4 + CTLs have been widely reported to contribute to virus clearance in numerous infectious diseases." (PMID 40386405, 2025). "Patients with CML have restricted CD4+ or CD8+ T‐cell clones, and reductions in TCR repertoire diversity with age may be associated with increased susceptibility to infectious disease." (PMID 40785616, 2025). "For instance, previous reports suggest a slow decline of CD4+ count with age in SIV-infected SMs compared to uninfected animals, which may contribute to the increased frequency of deaths caused by infectious diseases." (PMID 39258922, 2024). "Therefore, consistent with data in infectious disease models, CD4 T cells play a critical role in licensing CD8 T cells to differentiate into circulating memory populations." (PMID 37072485, 2023). "In infectious diseases anti-viral CD4+ CTL are mainly found in chronic viral infections." (PMID 37965314, 2023).
infectious disease (continued). "In the case of the pre-diagnostic markers for CD4+ T cells, the upregulated genes included ribosomal proteins (e.g. RPL39, RPL37, RPS28 and RPS21) that showed enrichments in pathways related to translation and “Infectious disease”." (PMID 35371081, 2022). "The levels of CD3+, CD4+, and CD8+ are correspondingly reduced in the presence of a weakened immune system and suppressed cellular immunity, exposing patients to a high risk of infectious diseases such as pathogenic infections." (PMID 35036430, 2022). "The role of CD4 CTL in swine infectious diseases is largely unknown, although some clues could be traced from literatures." (PMID 36798517, 2022). "Patients on ART for shorter than this time period may still be considered for transplantation provided that their CD4+ count exceeds the thresholds above, but consultation with an infectious diseases specialist is advised." (PMID 33240537, 2020). "The most frequently coded subtheme within this category was low CD4 count (n = 8), followed by high-risk setting (n = 6), non-compliance (n = 4), and other chronic or infectious disease (n = 4)." (PMID 32866154, 2020). "The low expression of CD43 on newborn CD4+ T cells and the inhibitory role of Siglec‐1 in adults could therefore have multiple implications on T cells during infectious diseases." (PMID 29266251, 2018). "Because IDO is known to suppress T-cell-mediated adaptive immune responses in a range of clinically relevant syndromes, including autoimmune, allergic, and infectious diseases, we also evaluated CD4+ and CD8+ T-cell responses specific for JEV antigen in surviving BL/6 and IDO-ablated mice 7 dpi." (PMID 27090635, 2016). "The distribution of the functional CD4+ T-cell subsets defines the quality of the adaptive immune response in infectious diseases including TB and several reports indicate that, at least in animal preclinical models, poly-functional CD4+ T cells mediate protection." (PMID 27467705, 2016). "This could be due to the fact that patients become bed ridden or ambulatory as a result of many infectious diseases as their CD4 cell count decrease." (PMID 23806088, 2013). "In addition to the LCMV system, antiviral CD4+CTL activity has been documented in four other models of infectious disease using the in vivo CTL assay in conjunction with endogenously generated CD4+ effector T cell populations." (PMID 23565245, 2013). "We expect that our method using phenotypic classification of CD8+ and CD4+ T-cells will be a useful tool to identify the dynamics of TCRα/β genes in patients with various infectious diseases or tumors and may contribute to the immunotherapy of them." (PMID 22792299, 2012). "Acute CD4+ T-lymphopenia has also been observed in other infectious diseases and might be explained by the migration of circulating lymphocytes to inflamed tissues or by apoptotic cell death." (PMID 22905277, 2012). "Therefore, it is not surprising that there is a high degree of overlap in signals needed for generation of the CD4 T cells required for B cell help, given that antibody responses are essential for combating a vast array of infectious diseases." (PMID 21423809, 2011). "An increased frequency of severe infectious diseases in ABOi renal transplant recipients may be explained by rituximab-induced long-term immunological effects on CD4+ and CD8+ T cell counts and the prolonged depletion of B cell subsets together with compromised B cell responses." (PMID 41459482, 2025). "Thus, it is necessary to determine whether to induce CD4+ or CD8+ T-cell responses depending on the features of the relevant infectious disease and establish optimal immunization order based on the immune responses that provide the best protection." (PMID 37271785, 2023).